ACE (angiotensin I converting enzyme)
Diseases named in the same sentence as ACE in open-access papers (continued):
Sharing a sentence is not in itself a finding about the gene and the disease.
sarcoidosis (continued). "However, the value of serum ACE levels in the diagnosis of sarcoidosis remains controversial due to its inadequate sensitivity and specificity." (PMID 23991342, 2013). "Specific cutaneous lesions along with BAL lymphocytosis, high CD4/CD8 ratio and elevated serum ACE levels may be predictors of progressive disease in sarcoidosis." (PMID 23521826, 2013). "The presence of high levels of angiotensin-converting enzyme (ACE) in a patient with infiltrative heart disease may increase suspicion of sarcoidosis." (PMID 24826302, 2013). "Elevated serum ACE occurs in approximately 60% of patients with sarcoidosis." (PMID 23533847, 2013). "At least 5% of the elevated levels of ACE do not have an underlying sarcoidosis, so another diagnosis must be considered." (PMID 24826302, 2013). "Thus, whenever very high serum ACE is found in the evaluation of potential sarcoidosis cases, we recommend that evaluation for the W1197X and P1199L mutations should be considered." (PMID 20011602, 2009). "Genetically determined elevation of ACE level may lead to false diagnosis of sarcoidosis and consequently to unnecessary long-term immunosuppresive treatment." (PMID 20011602, 2009). "The source of serum ACE in sarcoidosis is believed to be epitheloid cells in granulomata." (PMID 18811966, 2008). "The finding of granulomas may lead to confusion with other granulomatous conditions including Crohn's disease and, particularly in the presence of a raised serum angiotensin converting enzyme (ACE), sarcoidosis." (PMID 17335577, 2007). "The question whether genotype corrected normal values might be able to increase the reliability of ACE serological concentrations as a marker of disease activity in sarcoidosis remains to be determined by further studies." (PMID 16042760, 2005). "Accumulated evidence from the data presented reveal that the predictive values of serum ACE in sarcoid patients are still under consideration and findings derived from these studies are controversial concerning its usefulness in assessing the disease severity and predicting the clinical outcome." (PMID 16042760, 2005). "Clinically, patients with sarcoidosis often exhibit systemic symptoms including fatigue, cough, and sometimes skin or ocular involvement, and may have supportive laboratory findings such as an elevated angiotensin-converting enzyme (ACE) level." (PMID 40232665, 2025). "Other typical etiologies, such as Lyme disease, sarcoidosis, myocarditis, or electrolyte abnormalities, were considered; however were excluded by lack of endemicity, normal serum angiotensin-converting enzyme (ACE) levels and several, complete electrolyte panels." (PMID 41399558, 2025). "Additionally, both diseases can present with elevated serum angiotensin-converting enzyme (ACE) levels, a marker often associated with sarcoidosis but not exclusively so." (PMID 39553098, 2024). "Similarly, β2-microglobulin, as a marker of lymphocytic activation, has also been reported as elevated in sarcoidosis patients, with often normal values of ACE, while elevated neopterin, a product of monocyte activation, has also been noted in some sarcoidosis cases, albeit lacking specificity." (PMID 39198811, 2024). "Specifically, cardiac involvement, a life-threatening sarcoidosis manifestation, is associated with low rather than elevated ACE levels in our cohort, in concordance with known data in the literature regarding the low sensitivity and specificity of ACE levels in cardiac sarcoidosis." (PMID 39768579, 2024). "Angiotensin-converting enzyme (ACE) levels can be elevated in around 50% of cases, but it is more closely associated with pulmonic disease and can be used as a screening test in those where sarcoidosis may be suspected." (PMID 39759670, 2024). "However, even though the serum ACE level is reported to be elevated in 75% of the patients with sarcoidosis, it is not considered diagnostic due to a high false positive level." (PMID 39816283, 2024).
sarcoidosis (continued). "Some identified genes that may be associated with increased susceptibility to sarcoidosis are butyrophilin-like 2 gene (BTNL2), annexin A11 (ANXA11), and angiotensin-converting enzyme (ACE) variants; these associations, however, show high variability across populations." (PMID 39274446, 2024). "Furthermore, ACE expression has been observed in granulomas in the autoimmune disease sarcoidosis." (PMID 36608122, 2023). "However, the relationship between elevated ACE and Ang II in sarcoidosis remains to be explored." (PMID 35615369, 2022). "In addition, the improvement of sarcoidosis markers, such as sIL-2R and ACE, further supported this hypothesis." (PMID 36221396, 2022). "Also, the level of angiotensin-converting enzyme (ACE) was measured for sarcoidosis." (PMID 29904593, 2018). "Thus, measuring serum levels of ACE may be helpful for monitoring the disease activity of sarcoidosis." (PMID 30154391, 2018). "One retrospective review of patients with biopsy-proven sarcoidosis and uveitis suggested that although the sensitivities of ACE and lysozyme are low in isolation, when both tests are used in combination with chest X-ray, over 80% of patients had at least one marker suggestive of sarcoidosis." (PMID 24987524, 2014). "Angiotensin converting enzyme (ACE) may be elevated in 60–70% of patients with sarcoidosis." (PMID 24987524, 2014). "Furthermore, the serum ACE level declined after treatment for sarcoidosis." (PMID 24716039, 2014). "Measurements of serum angiotensin converting enzyme (ACE) level reflect the disease activity but are not specific enough for diagnostic properties; normal serum ACE levels do not exclude the diagnosis of sarcoidosis, especially not in case of isolated ocular manifestation." (PMID 24734169, 2014). "However, the value of serum ACE levels in diagnosing or managing sarcoidosis remains controversial." (PMID 24826302, 2013). "However, multisystemic sarcoidosis could be diagnosed in view of homogenously enhancing mediastinal lymphadenopathy on CT scan thorax, tuberculin skin test negativity, elevated ACE levels, and nerve palsies." (PMID 20442843, 2009). "Since blood ACE elevation is often taken as a marker of disease activity (sarcoidosis and Gaucher diseases), it is important for clinicians and medical scientists to be aware of alternative genetic causes of elevated blood ACE that are not apparently linked to disease." (PMID 20011602, 2009). "Angiotensin Converting Enzyme (ACE) levels were 145 U/(elevated) and gallium scan showed focal accumulation of gallium in right hilar region with no other abnormal focal uptake elsewhere in the body which was typical of sarcoidosis, confirming the diagnosis of sarcoidosis." (PMID 20442843, 2009). "The serum level of angiotensin-converting enzyme (ACE) is elevated in over 50% of children with late-onset sarcoidosis, but the test is not specific for sarcoidosis, and many other disorders may be similarly associated with increased serum ACE activity." (PMID 18811966, 2008). "Thus, serum ACE level is elevated in 80% to 90% of patients with sarcoidosis." (PMID 17118178, 2006). "Tuberculosis and sarcoidosis were excluded by radiological and laboratory tests, including chest X-ray and QuantiFERON ®TB-Gold (QFT-G) test, and angiotensin-converting enzyme (ACE), respectively." (PMID 40138028, 2025). "Serum IgG4 levels and serum angiotensin-converting enzyme (ACE) were also measured, and the results were normal, ruling out IgG4-related disease and sarcoidosis." (PMID 41322879, 2025). "Parathyroid hormone (PTH) was suppressed, and angiotensin-converting enzyme (ACE) was elevated, raising the suspicion of sarcoidosis." (PMID 39677199, 2024). "Prediction of the sIL-2R level by the patient’s serum ACE level might, therefore, be potentially helpful in the evaluation of lung function or other non-invasive techniques, which can improve clinical outcomes and individual management plans for patients with sarcoidosis." (PMID 39896373, 2024).
sarcoidosis (continued). "Serum calcium and serum angiotensin-converting enzyme (ACE) levels were within normal limits, which made sarcoidosis less likely." (PMID 39099590, 2024). "Currently, blood biomarkers such as ACE, sIL-2R, CD163, CCL18, serum amyloid A, and CRP are employed to aid in the diagnosis and monitoring of sarcoidosis." (PMID 39852350, 2024). "Corroborating serum studies included elevated serum angiotensin-converting enzyme (ACE) level (91 U/L), correlating with a sarcoidosis diagnosis." (PMID 39650894, 2024). "Further laboratory investigation revealed a moderately high ACE level (78 IU/L) and a slightly higher than normal ESR level (25 mm/h), which supported a diagnosis of sarcoidosis." (PMID 36789320, 2023). "Hence, the serum ACE level can be used to monitor whether sarcoidosis is successfully treated." (PMID 37868968, 2023). "Although clinical laboratory testing of serum angiotensin-converting enzyme (ACE), lysozyme, neopterin, and soluble interleukin 2 receptor (sIL-2R), which are produced by activated T cells or macrophages, is used as a diagnostic marker for sarcoidosis, their diagnostic ability is not satisfactory." (PMID 35663496, 2022). "We have proposed that measuring the ACE level (ACE phenotyping) rather than ACE genotyping will be more informative for many purposes, including identification of associations of ACE levels with cardiovascular complications, as well as for diagnostic evaluation of sarcoidosis." (PMID 35996109, 2022). "Our study also showed that serum NSE levels significantly decreased after spontaneous remission of sarcoidosis and that serum NSE levels fluctuated along with serum ACE and sIL-2R levels during the clinical course in some patients." (PMID 35663496, 2022). "The level of Angiotensin-Converting Enzyme (ACE), which is a known marker for sarcoidosis and whose levels correlated with the amount of whole-body granuloma, was evaluated in 30 patients in the EN group and 70 patients in the non-EN group." (PMID 35811196, 2022). "Angiotensin converting enzyme (ACE) and the soluble interleukin-2 receptor (sIL-2R) are the most widely used biomarkers in sarcoidosis, though with suboptimal sensitivity and specificity." (PMID 34573900, 2021). "Serum tests that show promise for detection of sarcoidosis include serum CTO and sIL-2R which have higher sensitivity and specificity than the more commonly used sarcoid biomarkers ACE and lysozyme." (PMID 33036432, 2020). "In support of the sarcoidosis diagnosis elevated C-reactive protein (CRP), erythrocyte sedimentation rate, and angiotensin-converting enzyme (ACE) levels were found." (PMID 31771516, 2019). "This study showed that YKL-40, sIL-2R, ACE and hs-CRP were elevated in active sarcoidosis patients compared to inactive patients." (PMID 30154391, 2018). "In our patient, raised serum ACE and findings in HRCT chest was suggestive of possible sarcoidosis whereas highly positive Mantoux test, positive history of contact with tuberculosis patient, and response to ATT were in favor of tuberculosis." (PMID 28534271, 2017). "None of the INIU patients in the discovery cohort had evidence or were suspected of sarcoidosis (follow-up ≥ 1 year) and the difference in intraocular ACE levels between INIU and AMD remained significant after correcting for ACE modulatory agents." (PMID 28128370, 2017). "The concentrations of ACE, CRP, ESR, CXL9, CXCL10, and sIL2R were all significantly elevated in sarcoidosis subjects when compared to control subjects." (PMID 24199653, 2013). "Serum levels of CXCL9, CXCL10, and proteins associated with inflammation and/or disease activity (sIL2R, ACE, ESR and CRP) were measured in a prospective cohort of sarcoidosis subjects and controls." (PMID 24199653, 2013). "Normal ACE levels, as seen in several cases in this review, do not exclude sarcoidosis and were often present in patients with isolated salivary gland involvement or early-stage disease." (PMID 41226948, 2025).
sarcoidosis (continued). "For selected patients, additional tests may include tests for angiotensin-converting enzyme (ACE), antineutrophil cytoplasmic antibodies (ANCA), or anti-Scl70 antibody and muscle enzymes when sarcoidosis, vasculitis, scleroderma, or myositis is suspected." (PMID 41153501, 2025). "Previously ordered chest X-ray and CT chest, along with a normal angiotensin-converting enzyme (ACE) level, did not support findings consistent with sarcoidosis." (PMID 40151729, 2025). "Angiotensin-converting enzyme (ACE) level was elevated at 118 U/L (normal range: 8-65 U/L), which raised concern for sarcoidosis, although classic sarcoidosis findings were absent." (PMID 40964550, 2025). "A presumptive diagnosis of indolent sarcoidosis was made keeping in mind the non-necrotising granuloma despite a normal serum ACE (Angiotensin-Converting Enzyme) level." (PMID 40662041, 2025). "While a normal ACE level does not exclude the diagnosis, an elevated ACE can help differentiate sarcoidosis from other granulomatous diseases when considered alongside clinical and laboratory findings." (PMID 41383541, 2025). "Serum ACE, although non-specific, reflects granuloma burden and is elevated in approximately 60% to 80% of active sarcoidosis cases." (PMID 40741038, 2025). "ACE and CHT are most commonly used as biomarkers in diagnosing and treating sarcoidosis." (PMID 40386527, 2025). "The family history of sarcoidosis (mother) raised suspicion in our case, but imaging and angiotensin-converting enzyme (ACE) levels did not support this diagnosis." (PMID 41487858, 2025). "While elevated ACE levels are detected in 30% to 80% of patients with sarcoidosis at diagnosis, these levels do not necessarily align with the severity of chest X-rays." (PMID 39896373, 2024). "Diagnostic imaging and histopathological evaluation confirmed stage 1 sarcoidosis, characterized by non-caseating granulomas and elevated angiotensin-converting enzyme (ACE) levels." (PMID 39416579, 2024). "While being monitored regularly, the patient developed cutaneous calcinosis as well as increased levels of ACE and vitamin D. A biopsy of the palm lesion revealed a non-caseating sarcoidal granuloma, confirming the diagnosis of sarcoidosis." (PMID 39286669, 2024). "Sarcoidosis was ruled out by an ophthalmologist’s and pulmonologist’s examination [based on angiotensin-converting enzyme (ACE) serum activity, normal chitotriosidase values, bronchoscopy, chest MSCT and no ocular manifestation of sarcoidosis]." (PMID 39005653, 2024). "In a multivariate analysis using a Cox proportional hazards regression model, it was found that sarcoidosis, non-Hodgkin’s lymphoma, lack of ACE inhibitor use, cirrhosis, and interstitial lung disease significantly increased the risk of elevated ACE levels." (PMID 39768579, 2024). "Elevated ACE levels had a positive predictive value of 12.76% and a negative predictive value of 94.6% for the diagnosis of sarcoidosis in our cohort, with a sensitivity of 63.5% and a specificity of 59.5%." (PMID 39768579, 2024). "Several diagnostic investigations are suggestive of a granulomatous disorder, including immunohistochemical stains of microorganisms (TB, syphilis, fungi), as well as serological analysis of ACE, ANCA, and ASCA levels to investigate for sarcoidosis, GPA and CD, respectively." (PMID 39110261, 2024). "ACEIs erode the negative predictive value of ACE activity, which makes it necessary to examine the use of drugs in patients with sarcoidosis." (PMID 38611622, 2024). "Though a tissue diagnosis could not be made, the combination of hypercalcaemia, increased serum ACE levels and bilateral hilar lymphadenopathy (seen on CT and PET scans) are highly suspicious for sarcoidosis." (PMID 39742164, 2024). "Further investigations, including Angiotensin Converting Enzyme (ACE) titration, bronchoscopy, bronchoalveolar lavage, and EndoBronchial UltraSound-guided TransBronchial Needle Aspiration (EBUS-TBNA), confirmed the diagnosis of sarcoidosis." (PMID 38534883, 2024).
sarcoidosis (continued). "Depending on chest radiography findings, the serum angiotensin-converting enzyme (ACE) level can be measured to exclude sarcoidosis, which can be best ruled out histologically (see histological features)." (PMID 39410007, 2024). "Unfortunately, ACE levels did not correlate with extra-ocular involvement of sarcoidosis, which is in line with previous studies." (PMID 39768579, 2024). "ACE levels are a non-specific serological marker with low specificity and sensitivity for sarcoidosis and a poor positive predictive value." (PMID 39768579, 2024). "Overall, the findings of our study suggest that ACE testing is not an optimal biomarker for diagnosing, tracking, or assessing the severity of sarcoidosis." (PMID 39768579, 2024). "Serum angiotensin-converting enzyme (ACE) levels were normal, suggesting that the changes to the lung were not due to sarcoidosis." (PMID 39624561, 2024). "This highlights that serum calcium and ACE levels are not always reliable for diagnosing sarcoidosis." (PMID 39391405, 2024). "A study of 172 patients with sarcoidosis showed that the serum ACE levels in patients with isolated CS were lower than the levels in those with non-isolated CS, implying that higher serum ACE levels were related to systemic lesions." (PMID 37868968, 2023). "Our findings supported the opinion that patients with sarcoidosis have higher mean Ca concentrations (Ca even correlated with ACE level), but it is not a good indicator of disease activity except in cases of hypercalcemia." (PMID 37510860, 2023). "ACEIs can reduce the serum ACE level, so the serum ACE level should not be used to diagnose and evaluate sarcoidosis in patients treated with ACEIs." (PMID 37868968, 2023). "Regarding the individual markers, elevated ACE levels supported sarcoidosis, but normal levels did not exclude disease." (PMID 35440697, 2023). "Serum ACE level is related to the systemic lesions of sarcoidosis, which is lower in patients with isolated sarcoidosis than in those with non-isolated sarcoidosis." (PMID 37868968, 2023). "Although, due to its poor specificity, an increase in ACE levels does not necessarily indicate the diagnosis of sarcoidosis." (PMID 36789320, 2023). "Tuberculosis and sarcoidosis were excluded due to negative results of QuantiFERON-TB Gold test, serum angiotensin-converting enzyme (ACE), serum lysozyme and chest computed tomography." (PMID 37522015, 2023). "Calcium concentration in patients with sarcoidosis correlated with several inflammatory markers and ACE, but not with vitamin D3 status and disease activity assessed with the use of typical clinical parameters." (PMID 37510860, 2023). "In GPA and sarcoidosis, ANCA-IFA and angiotensin converting enzyme (ACE) might help in making diagnosis." (PMID 37476904, 2023). "Tests for TB were negative, however, the ACE level was raised, and hence a probable diagnosis of sarcoidosis was made." (PMID 37203964, 2023). "The data show alveolar macrophages in smokers exhibit more ACE activity than those in non-smokers, and the activity is even more elevated in sarcoidosis patients." (PMID 36291609, 2022). "Systemic work-up and ACE levels are helpful in diagnosing atypical choroidal lesions in the absence of a confirmed sarcoidosis diagnosis." (PMID 36173484, 2022). "When comparing the serum levels of these markers between patients with sarcoidosis and those with nonsarcoidotic benign diseases, the levels of NSE, ACE, and sIL-2R were significantly higher in the sarcoidosis group." (PMID 35663496, 2022). "ACE is not specific for sarcoidosis, elevated serum ACE is also observed in tuberculosis, lung cancer, Hodgkin lymphoma, and cirrhosis of the liver." (PMID 35669693, 2022). "Moreover, ACE is still the first and only biomarker for the diagnosis and follow-up of sarcoidosis mentioned in the WASOG sarcoidosis guidelines." (PMID 35615369, 2022).